FPR3 (formyl peptide receptor 3)
Description:
May function as a pattern recognition G protein-coupled receptor (PRR/GPCR) involved in innate recognition of peptides derived from a specific set of bacterial pathogens or host mitochondria as pathogen- and damage-associated molecular patterns (PAMPs and DAMPs). Low affinity receptor for a restricted repertoire of bacterial N-formylated peptides including fMKKIML from L. monocytogenes and fMPKLNR from V. cholerae. Contrary to FPR1 and FPR2 does not act as a receptor for fMLF peptide. High affinity receptor for N-acetylated F2L peptide derived from the cleavage of heme-binding protein HEBP1. F2L peptide binding may trigger chemotaxis of monocytes and dendritic cells to facilitate tissue repair. Low affinity receptor for N-acetylated Ac2-26 peptide derived from ANXA1, an anti-inflammatory and pro-resolving agonist. Ac2-26 peptide binding can direct myeloid cell chemotaxis within the inflammatory site where ANXA1 is at high concentrations, but it can also lead to receptor desensitization to limit the inflammatory response. Receptor for MT-RNR2/humanin, a mitochondrial-derived peptide that has an anti-inflammatory role in resolution of inflammation. Peptide binding leads to conformational changes coupled to heterotrimeric G(i) protein signaling. Upon GDP to GTP conversion, G(i)-alpha subunit dissociates from G-beta and G-gamma subunits. Free G(i)-alpha subunit inhibits cyclic adenylate cyclase and cAMP synthesis whereas the G-beta and G-gamma dimer activates downstream phospholipase C-beta and phosphoinositide 3-kinase signaling cascades leading to Ca(2+) influx.
Synonyms: FMLP-R-II; FPRL2; FPRH1; FMLPY; RMLP-R-I; FML2_HUMAN; FPRH2
Tractability: Small molecule: it belongs to a druggable protein family. Antibody: its Gene Ontology location is reachable by antibodies, with high confidence; UniProt places it where antibodies can reach, with medium confidence; UniProt predicts a signal peptide or a membrane-spanning region. PROTAC: its protein half-life has been measured; a small molecule that binds it is known.
Gene: Protein-coding gene on chromosome 19 (51,795,137 to 51,826,324, forward strand). Ensembl gene ENSG00000187474.
Subcellular location: Cell membrane
Subcellular location (Human Protein Atlas): Plasma membrane; Primary cilium
Pathways (Reactome):
Signal Transduction: Formyl peptide receptors bind formyl peptides and many other ligands; G alpha (i) signalling events
Gene Ontology:
Molecular function: protein binding; complement receptor activity; N-formyl peptide receptor activity; G protein-coupled receptor activity
Biological process: complement receptor mediated signaling pathway; inflammatory response; phospholipase C-activating G protein-coupled receptor signaling pathway; positive regulation of cytosolic calcium ion concentration; signal transduction; G protein-coupled receptor signaling pathway
Cellular component: plasma membrane; membrane
Genetic constraint (gnomAD): Loss-of-function variants: 1 observed, 0.84 expected, observed/expected ratio (o/e) 1.19, 90% interval 0.29 to 1.91. That is too few expected variants to judge how well the gene tolerates losing a copy. Missense variants: 346 observed, 467.55 expected, observed/expected ratio (o/e) 0.74, 90% interval 0.68 to 0.81. Synonymous variants: 135 observed, 172.89 expected, observed/expected ratio (o/e) 0.78, 90% interval 0.68 to 0.9.
Homologues: Orthologues: chimpanzee FPR3 (99% identical), macaque FPR3 (88% identical), guinea pig FPR3 (52% identical). Paralogues in human: FPR2 (72% identical), FPR1 (58% identical), CMKLR1 (33% identical), C3AR1 (32% identical), GPR32 (32% identical), C5AR1 (29% identical), GPR33 (29% identical), C5AR2 (24% identical).